SOX9 (SRY-box transcription factor 9)
Diseases named in the same sentence as SOX9 in open-access papers (continued):
Sharing a sentence is not in itself a finding about the gene and the disease.
pulmonary fibrosis (12 papers, 2015 to 2025). Chronic progressive interstitial lung disorder characterized by the replacement of the lung tissue by connective tissue, leading to progressive dyspnea, respiratory failure, or right heart failure. "Strikingly, the increase in TGF-α–induced fibroblast activation and pulmonary fibrosis in TGFαOE mice was attenuated with the loss of SOX9, which supports the profibrotic function of SOX9." (PMID 34520400, 2021). "SOX9 has also been shown to participate in numerous other regulatory functions in various tissues and organs and to play a role in various fibrotic diseases including idiopathic and SSc-associated pulmonary fibrosis." (PMID 40308583, 2025). "Importantly, using 2 complementary mouse models of pulmonary fibrosis, we demonstrated that SOX9 upregulation in the distal lung fibroblasts causes severe fibrotic lung disease." (PMID 34520400, 2021). "Thus, our findings provide direct in vivo evidence that Sox9 expression in fibroblasts plays a pathogenic role during TGF-α–induced pulmonary fibrosis." (PMID 34520400, 2021). "In the present study, we evaluated whether Sox9 is upregulated in fibroblasts and the possible pathogenic role of Sox9, and its target genes, in fibroblast activation and pulmonary fibrosis." (PMID 34520400, 2021). "Prathibha R. Gajjala’s research shown that specifically deleting Sox9 in fibroblasts during TGF-α-induced pulmonary fibrosis reduces collagen deposition and enhances lung function." (PMID 39974732, 2025). "Using a mouse model of bleomycin-induced pulmonary fibrosis, we show that myofibroblast-specific Sox9 overexpression augments fibroblast activation and pulmonary fibrosis." (PMID 34520400, 2021). "Consistent with the findings in IPF lungs, we found that these SOX9-expressing fibroblasts accumulated in the distal fibrotic lung lesions during TGF-α–induced pulmonary fibrosis." (PMID 34520400, 2021). "To investigate the in vivo effects of fibroblast-specific Sox9 deletion in the pathogenesis of pulmonary fibrosis, we crossed TGFαOE mice with Sox9-floxed mice and Col1α2CreER mice." (PMID 34520400, 2021). "We demonstrated that both bleomycin- and TGF-α–induced pulmonary fibrosis depend on SOX9-driven increases in profibrotic gene networks and fibroblast activation." (PMID 34520400, 2021). "Taken together, our findings provide complementary in vivo evidence that Sox9 upregulation in fibroblasts is responsible for fibroblast activation and accumulation and plays an integral role in the pathogenesis of pulmonary fibrosis." (PMID 34520400, 2021). "Previous studies have identified the important roles of WT1 in both TGF-α– and bleomycin-induced pulmonary fibrosis, whereas the role of SOX9 has remained unclear." (PMID 34520400, 2021). "Our study demonstrates that Sox9 upregulation in fibroblasts contributes to pulmonary fibrosis and thus provides a therapeutic target for IPF." (PMID 34520400, 2021). "Both loss-of-function and gain-of-function studies suggest a pathological role for Sox9 in fibroblast activation and pulmonary fibrosis in 2 alternative mouse models of pulmonary fibrosis." (PMID 34520400, 2021). "SOX9 induces lung fibrosis mediated by transforming growth factor (TGF)-β1 repair signaling, characterized by inappropriate ECM deposition; this can result in the destruction of tissue architecture and function." (PMID 29915320, 2018). "In contrast, in inflammatory diseases—including bone and joint disorders, hepatitis, and pulmonary fibrosis—SOX9 activation exerts beneficial effects by enhancing macrophage activity, inhibiting it pyroptosis, and promoting tissue repair, making it a promising therapeutic target." (PMID 41293317, 2025). "Furthermore, in bleomycin-induced pulmonary fibrosis mouse model, they found that overexpressing SOX9 in MFs increases the activation of fibroblast as well as lead to lung fibrosis." (PMID 39974732, 2025). "In idiopathic pulmonary fibrosis, Sox9 participates in the migration and survival of fibroblasts." (PMID 35506305, 2022).
pulmonary fibrosis (continued). "Together, these studies identified SOX9 as a positive regulator of fibroblast activation in the pathogenesis of pulmonary fibrosis, illustrating the potential utility of targeting SOX9 or SOX9 downstream targets in the treatment of IPF and other fibrotic diseases." (PMID 34520400, 2021). "Although we indicated a role for SOX9 in fibroblast activation and pulmonary fibrosis, further work is necessary to determine the impact of SOX9 in other lung cells, including epithelial cells, during the initiation, maintenance, and resolution of pulmonary fibrosis." (PMID 34520400, 2021). "Overexpression of Sox9 in myofibroblasts augments bleomycin-induced pulmonary fibrosis." (PMID 34520400, 2021). "Therefore, we cannot rule out the possibility that other mechanisms are involved in SOX9-induced pulmonary fibrosis." (PMID 34520400, 2021). "In addition, we documented the important role of SOX9 in fibroblast activation using an alternative mouse model of bleomycin-induced pulmonary fibrosis." (PMID 34520400, 2021). "To further substantiate our findings, we investigated whether Sox9 overexpression augments bleomycin-induced pulmonary fibrosis." (PMID 34520400, 2021). "Sox9 is upregulated in a mouse model of TGF-α–induced pulmonary fibrosis." (PMID 34520400, 2021). "We demonstrated that the TGF-α/WT1 axis was involved in SOX9 upregulation in pulmonary fibrosis." (PMID 34520400, 2021). "Fibroblast-specific deletion of Sox9 attenuates TGF-α–induced pulmonary fibrosis in mice." (PMID 34520400, 2021). "Our genomic studies have identified several downstream targets of SOX9 that may have an important role in predicting the disease progression or mediating the pathology in lung fibrosis." (PMID 34520400, 2021). "To determine whether SOX9 is upregulated during TGF-α–induced pulmonary fibrosis, we measured the Sox9 levels in the total lung transcripts of TGF-α–overexpressing (TGFαOE) mice that developed severe fibrotic lung disease by 28 days after doxycycline (Dox) treatment." (PMID 34520400, 2021). "These new findings highlight how excessive SOX9 activity in fibroblasts can contribute to the progressive expansion of fibrotic lesions in the lung and that targeting the aberrant activation of SOX9 could be a therapeutic strategy to mitigate ongoing pulmonary fibrosis in IPF." (PMID 34520400, 2021). "We and previous studies found that there are P63+ and/or KRT5+ cells enriched in the damaged alveolar region of many lung disease patients (including those with COPD, pulmonary fibrosis and bronchiectasis), which could be the progeny of endogenous SOX9+ BCs in the middle of differentiation process." (PMID 29344809, 2018). "Moreover, SOX9 expression characterizes alveolar bipotential progenitors and surfactant-secreting cuboidal alveolar type 2 cells, which are altered in related lung diseases such as idiopathic pulmonary fibrosis." (PMID 26167915, 2015). "Therefore, SOX9 may be a potential target for treatment of pulmonary fibrosis." (PMID 37510994, 2023). "Overall, our findings indicate that SOX9 is a positive regulator of fibroblast activation by inducing migration, FMT, survival, and production of ECM in pulmonary fibrosis." (PMID 34520400, 2021). "Recent studies from our laboratory have shown that WT1 is upregulated in activated fibroblasts, and it coincides with the increase in profibrotic gene networks, including Sox9, during TGF-α–induced pulmonary fibrosis." (PMID 34520400, 2021). "Together, our findings suggest that WT1 functions as a positive regulator of SOX9 by directly binding to the SOX9 promoter in the distal lung fibroblasts during TGF-α–induced fibroblast activation and pulmonary fibrosis." (PMID 34520400, 2021). "During TGF-α–induced pulmonary fibrosis, WT1-positive fibroblasts have been shown to accumulate in distal fibrotic lesions, similar to SOX9-positive fibroblasts." (PMID 34520400, 2021).
pulmonary fibrosis (continued). "In this study, we showed that SOX9 was aberrantly activated in fibroblasts of distal lung fibrotic lesions in both human IPF and a mouse model of TGF-α–induced pulmonary fibrosis." (PMID 34520400, 2021). "Conversely, in a bleomycin-induced model of pulmonary fibrosis, diminished levels of SOX9 expression and the lack of IL-4 signaling through IL-4Ra in macrophages exacerbate the condition." (PMID 41293317, 2025). "Moreover, Sox9’s involvement in the TGF-β-stimulated myofibroblastic transition and ECM rearrangement was observed in cardiac, renal, liver, and lung fibrosis." (PMID 37175437, 2023). "Importantly, our in vivo studies demonstrate that fibroblast-specific deletion of Sox9 is sufficient to attenuate collagen deposition and improve lung function during TGF-α–induced pulmonary fibrosis." (PMID 34520400, 2021). "Compared with the control groups, the group without Sox9-expressing cells showed aggravated radiation-induced pulmonary fibrosis." (PMID 34215344, 2021). "To determine whether SOX9 alters TGF-α– and bleomycin-induced pulmonary fibrosis, we generated conditional fibroblast- or myofibroblast-specific Sox9-knockout or -overexpressing mice." (PMID 34520400, 2021). "To further improve the transplantation efficiency of SOX9+ BCs, we screened multiple drugs and found Pirfenidone, an FDA approved anti-pulmonary fibrosis drug could facilitate the SOX9+ BC transplantation efficiency significantly." (PMID 29344809, 2018). "Although the role of Sox9 in the epithelium during lung development is well documented, Sox9 expression in the distal fibroblasts of the lung and its potential role in fibroblast activation have never been explored in the context of pulmonary fibrosis to our knowledge." (PMID 34520400, 2021).
renal fibrosis (12 papers, 2017 to 2025). A final common manifestation of a wide variety of chronic kidney diseases characterized by glomerulosclerosis and tubulointerstitial fibrosis. "SOX9 has been associated with human renal fibrosis and is required for experimentally-induced renal fibrosis in mice." (PMID 37153766, 2023). "SOX9 serum is anticipated to emerge as a novel diagnostic biomarker for renal fibrosis." (PMID 39974732, 2025). "Several potential genes including SOX9 have been found to be biomarkers for renal fibrosis by using datasets (GSE76882, GSE22459), and this was also confirmed in cell experiments by RT-qPCR." (PMID 39974732, 2025). "Li et al26 showed that the knockdown or overexpression of SOX9 alleviated or exacerbated renal fibrosis, respectively." (PMID 38993791, 2024). "DOCK2, SLC1A3, SOX9, and TARP were identified as potential diagnostic genes for renal fibrosis, and the most relevant immune cells were identified." (PMID 37359552, 2023). "TGFβ-mediated increase in SOX9 expression has also been recently shown in mesenchymal fibroblasts to promote renal fibrosis." (PMID 33577554, 2021). "The high expression level of SOX9 has been found during renal fibrosis." (PMID 39974732, 2025). "Additionally, pathological collagen deposition is a hallmark of renal fibrosis, and we found that PGE2 treatment inhibited the expression of Col1a1 in Sox9+ cells and kidneys after AKI, which was further confirmed by Masson trichrome staining." (PMID 38801100, 2024). "In exploring the regulatory mechanisms of differentiation, our research focuses on the influence of PGE2 in moderating the population reduction of fibroblasts originating from the proliferation and differentiation of Sox9+ cells, ultimately facilitating a decrease in renal fibrosis." (PMID 38801100, 2024). "In murine UUO, we further evaluated whether iBETs regulated SOX9 and its potential relation to renal fibrosis." (PMID 36613933, 2022). "Importantly, the researchers identified that inhibiting SOX9 activity could hinder the progression of renal fibrosis." (PMID 40563434, 2025). "SOX9 overexpression promoted EMT, ECM deposition, and phosphorylated AKT up-regulation in renal tubular epithelial cells, while the PI3K inhibitor could reverse this phenomenon, indicating that SOX9 can promote renal fibrosis through the PI3K/AKT signaling pathway." (PMID 38993791, 2024). "We also found the expression of DOCK2, SLC1A3, SOX9, and TARP were higher in blood of renal fibrosis patients than healthy individuals." (PMID 37359552, 2023). "The expression levels of DOCK2, SLC1A3, SOX9, and TARP were higher in the renal fibrosis group than in the control group." (PMID 37359552, 2023). "Four candidate genes namely DOCK2, SLC1A3, SOX9 and TARP were identified as biomarkers of renal fibrosis, with the area under the ROC curve (AUC) values higher than 0.75." (PMID 37359552, 2023). "Our data describe, for the first time, how the iBET JQ1 inhibits the SOX9/COLIV signaling pathway in experimental GN and in cultured renal cells, identifying a novel mechanism involved in the beneficial effects of iBETs in renal fibrosis." (PMID 36613933, 2022). "Studies have shown that TGF-β1 can upregulate SOX9 expression to promote epithelial-to-mesenchymal transition (EMT) in cancer, atrial, and renal fibrosis." (PMID 35586685, 2022). "We found that hAD-MSC treatment upregulated the expression of tubular Sox9, promoted tubular regeneration, attenuated AKI, and mitigated subsequent renal fibrosis." (PMID 29050313, 2017). "In addition, SOX9 was induced by TGF-β in the kidney fibroblast, and it acted as an important downstream mediator of TGF-β signaling to promote renal fibrosis." (PMID 32763157, 2020).
lymph node metastasis (11 papers, 2017 to 2025). "In contrast, the SOX9 proportion score was significantly associated only with lymph node metastasis (β ═ 2.709, P ═ 0.0349)." (PMID 39907598, 2025). "The sole consideration of SOX2 expression only showed a tendency towards less lymph node metastasis and only the analysis in conjunction with SOX9 indicated the association with lower metastasis." (PMID 39180200, 2025). "Third, our results showed the expression of SOX9 was positively associated with lymph node metastasis, large tumor size, distant metastasis and a higher clinical stage." (PMID 29348895, 2017). "By contrast, the SOX9 proportion score was significantly associated only with lymph node metastasis, suggesting that the total immune staining score may provide a more comprehensive measure of SOX9’s overall impact." (PMID 39907598, 2025). "Since lymph node metastasis is associated with cancer cell migration, we explored whether the SOX9 gene regulated the invasiveness of cancer cells by using a Transwell invasion assay." (PMID 35159173, 2022). "In order to examine whether the expression of SOX9 and aldehyde dehydrogenase 1 (ALDH1) proteins is associated with lymph node metastasis in HGOC, we used immunohistochemistry to analyze SOX9 and ALDH1 protein expression in 39 HGOC samples with or without lymph node metastasis." (PMID 35159173, 2022). "We discovered elevated predominant cytoplasmic SOX9 expression in HGOC and found a strong correlation between cytoplasmic SOX9 and ALDH1A1 expression only in HGOC with lymph node metastasis." (PMID 35159173, 2022). "Among upregulated oncogenic proteins in HGOC, we found that transcription factor SOX9 showed a strong correlation with stemness-regulating ALDH1A1 and was localized predominantly in the cytoplasm of HGOC with lymph node metastasis." (PMID 35159173, 2022). "SOX9 was highly expressed in the T4 or tumors with lymph node metastasis or without treatment." (PMID 35740627, 2022). "Furthermore, Sox9 deletion increased the incidence of metastasis, with 6 of 11 AKPS mice harboring lymph node and liver metastases, and 1 of 11 mice having a lung metastasis, compared with only 2 of 11 AKP mice with lymph node metastases and 1 of 11 AKP mice with liver and lung metastases." (PMID 40179020, 2025). "Conversely, in CAFs, NR2F1 expression was higher in T3 or tumors with lymph node metastasis, TGFB1 was higher in larger T categories or without lymph node metastasis, and there was little difference in SOX9 expression." (PMID 35740627, 2022).
Barrett esophagus (10 papers, 2014 to 2022). Esophageal lesion lined with columnar metaplastic epithelium which is flat or villiform. "Injury induced by chronic acid reflux reactivates SOX9 expression, and triggers Barrett’s esophagus, a gastric/intestinal metaplasia that increases the risk of developing adenocarcinoma in the formerly squamous epithelium." (PMID 27880766, 2016). "SPNB2 is demonstrated to be highly expressed in the adipogenic process and can also be a TGF-β adapter that regulates notch signaling and SOX9 expression in esophageal adenocarcinoma." (PMID 34887920, 2021). "Co-expression of this antigen complex and SOX9 also characterises the ductal metaplasia of submucosal glands that occurs during the development of Barrett’s oesophagus." (PMID 30814526, 2019). "Given the reports of submucosal metaplasia after Barrett's esophagus radioablation, it remains to be seen if SOX9 expression coupled with high Activin A serum levels would be useful as an early detection marker." (PMID 26447543, 2015). "Eight cancer cell lines and two Barrett’s esophagus (BE) cell lines were immunoblotted for the expression of CSC- related genes SOX9, YAP1 and Shh." (PMID 24859412, 2014). "Thus, the GCTM-5 antigen marks SOX9 positive cells including metaplastic ductal cells in Barrett’s metaplasia." (PMID 30814526, 2019). "Barrett's esophagus (BE) can evolve to esophageal adenocarcinoma (EAC) through low-grade dysplasia and high-grade dysplasia (HGD), and SOX9 expression is significantly increased in the upper crypt epithelial cells in HGD." (PMID 26384302, 2015). "Because Smad3 was recently shown to interact with Notch1 in esophageal adenocarcinoma cells after treatment with TGF-β, we tested if N1ICD binding to the Sox9 promoter RBP-Jκ site was dependent on TGF-β signaling in lung ADC." (PMID 25004243, 2014). "Activin A increases SOX9 nuclear localization in the esophageal adenocarcinoma cell line FLO-1, suggesting that Activin A could also regulate SOX9 in the Sertoli cells." (PMID 36362374, 2022).